TERT (telomerase reverse transcriptase)
Diseases named in the same sentence as TERT in open-access papers (continued):
Sharing a sentence is not in itself a finding about the gene and the disease.
thyroid cancer (continued). "In this regard, the capacity of GABPA to bind to mutant TERT promoters in thyroid cancer was reported through ChIP assays on the K1 papillary thyroid carcinoma cell line." (PMID 35053525, 2022). "In conclusion, our data suggest that the ETS-mediated regulation of TERT mutant promoter in thyroid cancers likely differs from that reported in other tumors carrying TPMs in the same hotspots." (PMID 35053525, 2022). "To assess which ETS factors are relevant in the control of TERT promoter in thyroid cancer specimens, we adopted an unbiased approach, evaluating their reported binding preferences and expression patterns in thyroid tumors and cell lines." (PMID 35053525, 2022). "The results point to the co‐FISH assay for the 5p‐end and TERT locus as a promising cytogenetic tool for determining thyroid cancer prognosis." (PMID 35979662, 2022). "In the present cohort, 39.4% of thyroid cancers with these high‐risk mutations were detected, including five cases of BRAF V600E mutation (one combined with TERT mutation), two cases of TERT mutations and seven gene fusions." (PMID 35247035, 2022). "In this study, we systematically knocked down each of the 20 ETS factors expressed in thyroid tumors and screened their effects on TERT expression in seven thyroid cancer cell lines with defined TPM status." (PMID 35053525, 2022). "Of note, the half‐life of TERC RNA is more than 2 weeks in TERT‐positive, non‐thyroid cancer cells, and consistently, TERC was observed to be more enriched in primary tumours across the TCGA pan‐cancers." (PMID 36394204, 2022). "During the development and progression of thyroid carcinomas (TCs), TERT induction and telomerase activation is in general required to maintain telomere length, thereby conferring TC cells with immortal and aggressive phenotypes." (PMID 36394204, 2022). "This discrepancy between brain tumors and thyroid cancer can be explained by alternative mechanism of ETS factors on TERT regulation among these cancer types." (PMID 34221969, 2021). "To study the roles of miR-195-5p and TERT in thyroid cancer cells and normal cells, we detected the miR-195-5p and TERT expressions by immunohistochemistry, qRT-PCR,and western blot." (PMID 34482792, 2021). "Of all genetics associated with well-differentiated thyroid cancer, BRAF and TERT mutations are the most robust prognosticators of aggressive disease." (PMID 34702207, 2021). "Further investigation on the mechanism of YK-4-279 on ETS recruitment of co-activators on TERT promoter in thyroid cancer is required." (PMID 34221969, 2021). "In summary, overexpression of miR-195-5p inhibits the regulatory effect of TERT on the proliferation, apoptosis, and movement of thyroid cancer cells, CAL-62." (PMID 34482792, 2021). "The BRAF V600E and the MAPK pathway was reported to activate several ETS transcription factors, the latter then selectively bonded to the mutant promoter of TERT and led to TERT activation in thyroid cancer." (PMID 34221969, 2021). "In this study, 73 matched neoplastic tissue and plasma DNA samples and 54 plasma DNA samples from healthy individuals were examined for the diagnostic utility of ctDNA in thyroid cancers focusing on BRAF, KRAS, NRAS, and TERT promoter mutations." (PMID 33915745, 2021). "The activation of FOS facilitated the transcription of GABPB1, a member of the ETS transcription factor family, thereby enhancing TERT expression in thyroid cancer cells bearing mutant TERT promoter." (PMID 33669363, 2021).
thyroid cancer (continued). "The aggressive behavior of thyroid cancer with RAS mutations, initially reported, has been overturned by the recent finding of the cooperative role of TERT mutations." (PMID 34359686, 2021). "Apart from clinicopathological characteristics, several genic features (such as BRAF, TERT, and RET) can be applied for risk stratification and prognostic scoring systems of thyroid cancer patients." (PMID 35433709, 2021). "In well-differentiated thyroid cancer, telomerase reverse transcriptase (TERT) promoter and B-type raf proto-oncogene V600E (BRAFV600E) mutations have demonstrated particular utility in predicting disease and high risk clinicopathology." (PMID 34702207, 2021). "In our current study, we also demonstrate that miR-195-5p is lowly expressed in thyroid cancer tissues and cells, and TERT mRNA and protein are highly expressed." (PMID 34482792, 2021). "Thirty-two somatic mutations were identified exclusively in known thyroid cancer genes (BRAF, KRAS, NRAS, and TERT)." (PMID 33821390, 2021). "Thus, ETS inhibitor YK-4-279 suppressed TERT expression and conferred anti-tumor activity in a TERT promoter mutation-independent manner, and it could be a potential agent for the treatment of advanced thyroid cancers." (PMID 34221969, 2021). "Consistently, treatment of thyroid cancer cells with YK-4-279 for 24 h significantly decreased TERT expression in either TERT promoter-WT or TERT promoter-mutant cell lines in a dose-dependent manner." (PMID 34221969, 2021). "Inhibition of TERT expression in thyroid cancer cells significantly reduced cell viability, migration, and invasion in vitro and suppressed tumor growth in vivo." (PMID 34221969, 2021). "A combination of BRAFV600E and TERT has been noticed in all thyroid cancer histotypes, but it has specific significance in PTC." (PMID 34684168, 2021). "Recently, two C>T mutations in the promoter of TERT gene, located at -124 and -146 bp upstream of TERT’s translational start site and designated as C228T and C250T, have been described in several cancer types, including thyroid carcinomas." (PMID 33776938, 2021). "Of note, ddPCR is a promising platform to absolute quantification of copy number alteration, a distinct mechanism that results in TERT upregulation and increased activity and that has been documented in thyroid carcinomas." (PMID 33776938, 2021). "For instance, there are exciting advanced being made in the research setting on development of new molecular markers (e.g., TERT expression) that can improve prognostication and treatment of thyroid cancer." (PMID 33162941, 2020). "Because telomerase plays a key role in carcinogenesis, understanding TERT regulation and telomerase activation in thyroid cancer is critical to understanding its pathogenesis." (PMID 32849278, 2020). "Their results showed that FOXD2-AS1 acts as a ceRNA for miR-7-5p, upregulating the expression of TERT, which increases the CSCs properties and anoikis resistance in thyroid cancer cells." (PMID 32760219, 2020). "We will also explore in detail the different TERT regulatory strategies and how TERT is reactivated in thyroid cancer cells, specifically." (PMID 32849278, 2020). "In this review, we summarize our current understanding of the multiple mechanisms of TERT regulation in thyroid cancer." (PMID 32849278, 2020). "The results of this study provide evidence that the majority of well differentiated T4 thyroid cancers have mutations in BRAF and/or TERT promoter regions." (PMID 32415114, 2020). "Upregulation of TERT expression and resulting telomerase activity occurs in the large majority of malignancies, including thyroid cancer." (PMID 32849278, 2020).
thyroid cancer (continued). "In this review we will briefly introduce TERT and telomerase activity as it pertains to thyroid cancer and, highlight the effects of TERT on cancer cells." (PMID 32849278, 2020). "Overall, advanced T4 thyroid cancers more frequently harbored TERT mutations and had a 10-fold higher rate of co-occurring BRAF and TERT mutations." (PMID 32415114, 2020). "Out of 28 protein-coding, five genes; TERT, FLT4, DUSP6, USP10 and POMC have already been implicated in thyroid cancer." (PMID 32324757, 2020). "In this study, we provide genetic characterization of locally advanced T4 well differentiated thyroid cancer and demonstrate that the majority (19/25, 76%) are driven by BRAF V600E mutation and 12 (48%) also harbor co-existent TERT promoter mutations." (PMID 32415114, 2020). "This is consistent with findings in other series of well differentiated thyroid cancer, where BRAF mutations in tumors>1 cm in size and particularly co-occurring BRAF and TERT mutations were associated with a significantly higher risk of disease recurrence." (PMID 32415114, 2020). "In summary, the results of this study show that T4 well differentiated thyroid cancer develops primarily via BRAF V600E-initiated pathway, and more than half of them also carry TERT mutations." (PMID 32415114, 2020). "The activating GA Binding Protein Transcription Factor Subunit Alpha (GABPA), a member of the ETS family, binds at the TERT promoter mutation site as a heterotetramer with its counterpart, GABPB, in multiple cancer types, including thyroid cancer." (PMID 32849278, 2020). "The most common oncogenic duet that has been investigated for its association with aggressive thyroid cancer phenotype is BRAFV600E and mutated TERT promoter." (PMID 32751138, 2020). "GSC is a TERT activator and was variously expressed in both thyroid cancer and normal thyroid cells." (PMID 33329574, 2020). "In the molecular diagnosis of thyroid cancer, the related molecular markers include TERT, BRAF, PAX8/ PPARγ, RAS and RET/PTC26." (PMID 31949496, 2020). "Comparatively, normal thyroid tissue showed overall low levels of methylation throughout the TERT promoter compared to the thyroid cancer cell lines." (PMID 32849278, 2020). "Average frequencies of TERT promoter mutations in DTC, papillary (PTC), and follicular (FTC) thyroid carcinomas were 10.9%, 10.6%, and 15.1%, respectively." (PMID 31655978, 2020). "Co-occurrence of TERT/BRAFV600E mutations were present in 12/25 (48%) of T4 and 5/102 (5%) of T1/T2 thyroid carcinomas." (PMID 32415114, 2020). "Of note, studies have reported that overexpression of TERT not only promotes the development and aggressive behaviors of thyroid cancer cells, but also predicts early recurrence in thyroid cancer patients." (PMID 31024447, 2019). "TERT, a predominant determinant for controlling the activity of telomerase, was likely to coexist with BRAF V600E mutation in thyroid cancer." (PMID 31300059, 2019). "Novel functional mutations in TERT promoter, including single‐nucleotide variants and duplications, lead to increased TERT promoter activity, highlighting additional mechanisms of TERT activation in thyroid cancer." (PMID 31408918, 2019). "This study confirms the increased prevalence of TERT promoter mutations and CNV in advanced thyroid cancers and describes novel functional alterations in the TERT gene promoter, including a point mutation and small duplication." (PMID 31408918, 2019). "Our study also shows a higher prevalence of TERT copy number gains in aggressive thyroid cancer types, particularly in HCC and PDTC." (PMID 31408918, 2019). "Several studies have demonstrated that overexpression of TERT is not only involved the development and aggressive behaviors of thyroid cancer cells, but also predicts early recurrence in thyroid cancer patients." (PMID 31024447, 2019). "It has been recognized that TERT promoter was more frequently detected in poorly differentiated and undifferentiated thyroid cancers." (PMID 30915113, 2019).
thyroid cancer (continued). "It has been demonstrated that clinical prognosis is significantly worse when the BRAF mutation is present along with a TERT mutation, complicating the role that BRAF has in thyroid cancer." (PMID 31443155, 2019). "FOXD2-AS1 acts as a competitive endogenous RNA (ceRNA) for miR-7-5p, up-regulating the expression of telomerase reverse transcriptase (TERT), which further promotes the cancer stem cells features and anoikis resistance in thyroid cancer cells." (PMID 31024447, 2019). "Both c.‐332C > T and c.‐104_‐83dup mutations showed a stimulatory effect on transcriptional activity of TERT promoter in normal and cancer thyroid cells as we showed using luciferase reporter assay approach." (PMID 31408918, 2019). "In summary, our study demonstrates that FOXD2-AS1 functions as a competing endogenous RNA to upregulate TERT expression by sponging miR-7-5p in thyroid cancer." (PMID 31024447, 2019). "BRAF V600E promoter mutation, in combination with TERT or RAS mutation, was recognized as clinically important diagnostic and prognostic genetic markers for thyroid cancer." (PMID 31300059, 2019). "We also explored the wide spectrum of signaling pathways converging on TERT promoter and the possible still poorly understood connections with the biological mechanisms already described in thyroid cancer biological settings." (PMID 31200515, 2019). "For example, in thyroid carcinoma, lncRNA FOXD2 adjacent opposite strand RNA 1(FOXD2-AS1) promotes the cancer stem cell features and anoikis resistance in thyroid cancer cells via inhibiting the miR-7-5p/telomerase reverse transcriptase (TERT) axis." (PMID 31744046, 2019). "The discovery of TERT promoter mutations in thyroid cancer were found to be useful, as 9.4% of PTC have TERT promoter mutations that are associated with older patients, higher MACIS scores and high risk of recurrence." (PMID 30285776, 2018). "The discovery of novel molecular-based prognostic markers for thyroid cancer, such as RET-PTC, RAS, BRAF (V600E), PTEN and TERT mutations, are among the most notable developments in thyroid cancer-related medicine." (PMID 29254191, 2017). "Mutations in the TERT promoter, ALK rearrangement, and the BRAF V600E mutation are associated with aggressive clinicopathologic features in thyroid cancers." (PMID 26857243, 2016). "Our study demonstrated that Korean patients have a higher BRAF V600E prevalence and lower prevalence of the TERT promoter mutation and ALK rearrangement in thyroid cancers than do Western patients." (PMID 26857243, 2016). "We performed Sanger sequencing to detect BRAF V600E and TERT promoter mutations and both immunohistochemistry and fluorescence in situ hybridization to identify ALK rearrangement on 243 thyroid cancers." (PMID 26857243, 2016). "We aimed to investigate the prevalence of TERT promoter and ALK mutations in thyroid cancer patients with a high prevalence of the BRAF V600E mutation and their potential contribution for the risk stratification of these patients." (PMID 26857243, 2016). "Therefore, it is suggested that TERT promoter mutations are involved only in the tumorigenesis of follicular-cell derived thyroid cancers, particularly in aggressive subtypes, and may occur as a late molecular-genetic event that induces dedifferentiation of WDTCs." (PMID 26857243, 2016). "However, a number of previous reports disagree on whether TERT promoter mutations are responsible for elevated TERT expression or low patient survival rate in a variety of cancers, including, but not limited to, cutaneous melanoma, thyroid cancer, bladder cancer, and HCC." (PMID 26575952, 2016). "TERT promoter mutations assessed on thyroid fine-needle aspiration biopsy (FNAB) were also evaluated to discriminate between benign and malignant thyroid tumors." (PMID 27438857, 2016).
thyroid cancer (continued). "It was documented that a significant increase in TERT promoter mutations occurred from well-differentiated PTC and FTC to anaplastic thyroid cancer (ATC), the most aggressive thyroid cancer." (PMID 27438857, 2016). "This study, together with recent studies in other cancers, unequivocally establishes an important role of TERT SNPs in cancer development, especially human thyroid cancer." (PMID 27185198, 2016). "To do this, we first compared the sensitivity and specificity of Sanger sequencing and castPCR by using mixed DNA from one C228T-positive and one wild-type TERT promoter-carrying thyroid cancer line." (PMID 25474136, 2014). "This study evaluated the reliability of droplet digital polymerase chain reaction (ddPCR) for detecting TERT promoter (pTERT) mutations in formalin-fixed, paraffin-embedded (FFPE) thyroid cancer samples and examined their association with clinicopathological features." (PMID 41683917, 2026). "Univariate binary logistic regression analysis identified age, T stage, N stage, unilateral thyroid involvement, maximum tumor diameter, extra-glandular invasion, and RET, TERT, and BRAF gene mutations as factors significantly associated with lung metastasis in thyroid cancer." (PMID 41306438, 2025). "Up till now, none of the few studies performed on TERT amplification as a mechanism of TERT re-expression and telomerase activation in thyroid cancer has appraised the impact of TERT amplification on the clinical course (recurrence and survival) of PTC patients." (PMID 40272676, 2025). "Likewise, TERT amplification was evaluated in 13 thyroid cancer cell lines derived from pTs, with different degrees of differentiation, or from DMs or LNMs of thyroid tumors." (PMID 40272676, 2025). "TERT-p mutations are uncommon in paediatric thyroid carcinomas, including in several large paediatric studies that did not identify any TERT-p mutations." (PMID 40361475, 2025). "The quantification of TERT mRNA may serve as a prognostic indicator in many different tumors, such as thyroid carcinoma, Wilm’s tumor, non-small cell lung cancers and neuroblastoma." (PMID 39858033, 2025). "This association of TERT and PI3K signaling pathway may shed some light on the role of TERT in the pathogenesis of thyroid cancer as well as RAI-RTCs." (PMID 39473507, 2024). "Our findings suggest a possible association between additional TERT promoter mutations, alongside low TDS and SLC5A5 mRNA expression in NTRK-rearranged metastatic RAI-resistant thyroid cancers and the re-induction failure of RAI uptake following larotrectinib treatment." (PMID 38642578, 2024). "Thus, miRNA-138 expression is downregulated in thyroid cancer, which promotes TERT overexpression and correlates with the cancer stage and the invasive phenotype." (PMID 39769169, 2024). "The occurrence rates of TERT mutations in thyroid cancer do not differ significantly among Asians, Europeans, and Americans." (PMID 38607456, 2024). "In this study we comprehensively analyzed the correlation between TERT methylation and clinical outcomes of PTC by enrolling 571 samples from the TCGA thyroid cancer database, and found that patients with TERT hypermethylation had unfavorable OS, DSS, DFI and PFI." (PMID 38313800, 2024). "In addition, TERT was a potential prognostic biomarker in diagnosis and prognosis of cancer, including breast cancer, thyroid cancer, and bladder cancer." (PMID 38431660, 2024). "Lastly, BRAF and TERT assessments were conducted in a limited cohort, insufficient to represent the entire study population, and there is a paucity of data on the molecular characteristics and genetic information for thyroid cancer." (PMID 38711981, 2024).